MYO18A (myosin XVIIIA)
Description:
[Isoform TIAF1]: Inhibits the cytotoxic effects of TNF and overexpressed TNF receptor adapters TRADD, FADD, and RIPK1. Involved in TGF-beta1 inhibition of IkappaB-alpha expression and suppression of TNF-mediated IkappaB-alpha degradation. May link Golgi membranes to the cytoskeleton and participate in the tensile force required for vesicle budding from the Golgi. Thereby, may play a role in Golgi membrane trafficking and could indirectly give its flattened shape to the Golgi apparatus. Alternatively, in concert with LURAP1 and CDC42BPA/CDC42BPB, has been involved in modulating lamellar actomyosin retrograde flow that is crucial to cell protrusion and migration. May be involved in the maintenance of the stromal cell architectures required for cell to cell contact (By similarity). Regulates trafficking, expression, and activation of innate immune receptors on macrophages. Plays a role to suppress inflammatory responsiveness of macrophages via a mechanism that modulates CD14 trafficking. Acts as a receptor of surfactant-associated protein A (SFTPA1/SP-A) and plays an important role in internalization and clearance of SFTPA1-opsonized S.aureus by alveolar macrophages. Strongly enhances natural killer cell cytotoxicity.
Synonyms: MAJN; SP-R210; KIAA0216; MYSPDZ; TIAF1; SPR210
Tractability: Antibody: UniProt places it where antibodies can reach, with high confidence. PROTAC: ubiquitination databases record sites on it; its protein half-life has been measured.
Gene: Protein-coding gene on chromosome 17 (29,071,119 to 29,180,456, reverse strand). Ensembl gene ENSG00000196535.
Subcellular location: Nucleus (Isoform TIAF1); Golgi apparatus; Golgi apparatus, trans-Golgi network; Golgi outpost; Cytoplasm, cytoskeleton, microtubule organizing center; Endoplasmic reticulum-Golgi intermediate compartment (Isoform 1); Cytoplasm, cytoskeleton; Cytoplasm (Isoform 2); Cell surface (Isoform 5)
Pathways (Reactome):
Disease: Signaling by FGFR1 in disease; Signaling by FLT3 fusion proteins; Signaling by cytosolic FGFR1 fusion mutants
Gene Ontology:
Molecular function: actin filament binding; ADP binding; ATP binding; ATP hydrolysis activity; protein binding; RNA binding; ATP-dependent activity, acting on DNA; DNA binding
Biological process: actomyosin structure organization; asymmetric Golgi ribbon formation; cell migration; Golgi organization; Golgi ribbon formation; Golgi vesicle budding; negative regulation of apoptotic process; positive regulation of opsonization; positive regulation of protein secretion; regulation of macrophage activation; DNA metabolic process
Cellular component: actomyosin; cell surface; cytoplasm; Golgi apparatus; membrane; trans-Golgi network; endoplasmic reticulum-Golgi intermediate compartment; myosin filament; myosin II complex; postsynaptic Golgi apparatus; actin cytoskeleton; cytoskeleton; Golgi membrane; microtubule organizing center; myosin complex
Genetic constraint (gnomAD): Loss-of-function variants: 77 observed, 224.62 expected, observed/expected ratio (o/e) 0.34, 90% interval 0.28 to 0.41. The upper end of that interval is the gene's LOEUF score, 0.41, which puts it in group 1 of 6, group 1 being the genes least tolerant of losing a copy. Missense variants: 2,189 observed, 2,690.9 expected, observed/expected ratio (o/e) 0.81, 90% interval 0.78 to 0.84. Synonymous variants: 968 observed, 1,082 expected, observed/expected ratio (o/e) 0.89, 90% interval 0.85 to 0.94.
Homologues: Orthologues: chimpanzee MYO18A (99% identical), macaque MYO18A (98% identical), pig MYO18A (96% identical), guinea pig MYO18A (94% identical), rabbit MYO18A (94% identical), rat Myo18a (81% identical), mouse Myo18a (74% identical), zebrafish myo18aa (71% identical), tropical clawed frog MYO18A (70% identical), zebrafish myo18ab (67% identical), Drosophila melanogaster Mhcl (39% identical), Caenorhabditis elegans nmy-3 (19% identical). Paralogues in human: MYO18B (40% identical), MYH3 (22% identical), MYH6 (22% identical), MYH7 (22% identical), MYH8 (22% identical), MYH7B (22% identical), MYH2 (22% identical), MYH10 (21% identical), MYH1 (21% identical), MYH11 (21% identical), MYH4 (21% identical), MYH13 (21% identical), and 32 more.
Diseases named in the same sentence as MYO18A in open-access papers:
MYO18A is named in the same sentence as 33 diseases in open-access papers, as found by Europe PMC text mining. Sharing a sentence is not in itself a finding about the gene and the disease. The quoted sentences say what the papers report.
lung carcinoma (4 papers, 2013 to 2019). "We have therefore evaluated whether SNX27 and MYO18A also regulate lung cancer cell motilities through the PIX/GIT1 complex." (PMID 26462147, 2015).
prostate carcinoma (4 papers, 2020 to 2024). A carcinoma that arises from epithelial cells of the prostate gland. "MYO18A is overexpressed in metastatic prostate cancer cells, which may help reduce NM2A stress fibers." (PMID 32670437, 2020). "Overexpression of MYO18A was observed in metastatic prostate cancer cell lines in a previous study." (PMID 33194745, 2020). "Interestingly, among prostate cancer cell lines, MYO18A expression was shown to be higher in a cell line with higher metastatic potential, and the authors inferred, based on knockdown studies, that effects of MYO18A on actin organization and motility could contribute to metastasis." (PMID 38784114, 2024). "However, MYO18A is not overexpressed in prostate cancer tissues and has not been reported in other cancers." (PMID 32670437, 2020).
breast carcinoma (2 papers, 2014 to 2025). "Inclusion of exon 40 in MYO18A has been reported to promote a mesenchymal phenotype in breast cancer cells and is associated with poor prognosis in patients with triple-negative breast cancer." (PMID 40316533, 2025). "We found that exon 40 in the MYO18A gene and exon 3 in the NFYA gene were not only downregulated in Snord67 knockout cells, but also positively correlated with Snord67 expression levels in breast cancer patients." (PMID 40316533, 2025).
breast tumor (2 papers, 2014 to 2025). "That is, in patients whose LN metastasis displayed increased Snord67 expression relative to the primary breast tumor, the inclusion of MYO18A exon 40 and NFYA exon 3 was also increased in the LN tumor relative to the primary breast tumor." (PMID 40316533, 2025). "Moreover, the change in PSI for these two alternative exons significantly correlated with the change in Snord67 expression in matched pairs of primary breast tumors and LN metastases (MYO18A exon 40: Pearson r = 0.54, p = 0.0066; NFYA exon 3: Pearson r = 0.51, p = 0.011)." (PMID 40316533, 2025). "Two of the most strongly affected alternative exons in murine NSCs,Myo18a exon 38 and Erbin exon 21 (Erbb2ip, a direct binding-partner of the breastcancer oncogene HER2/Erbb2) were conserved in the human genome and detected in thetranscriptomes of all analyzed breast tumors and controls." (PMID 25380226, 2014).
metastatic tumors (2 papers, 2015 to 2020). "In PCa, Myo1b, Myo6, Myo9b, Myo10, and Myo18a were expressed at higher levels in high metastatic potential cells, and especially Myo1b and Myo10 were expressed at higher levels in metastatic tumors." (PMID 33292248, 2020).
cataract (1 paper, 2025). Partial or complete opacity of the crystalline lens of one or both eyes that decreases visual acuity and eventually results in blindness. "Specifically, proteins including ACTN4, DCTN1, MYO18A, TUBA1C, TBCB, and TUBB4A, were downregulated in all cataract groups compared to controls." (PMID 41283652, 2025).
diabetes mellitus (1 paper, 2023). A metabolic disorder characterized by abnormally high blood sugar levels due to diminished production of insulin or insulin resistance/desensitization. "Novel targets include MYO18A, SEC16A, CCNB1, MAD2L1, hsa-mir-4315, hsa-mir-6134, hsa-mir-9500, KIFC3, FBL (fibrillarin), TUBA1A and GFI1B might have crucial biologic functions in the pathogenesis of patients with diabetes mellitus and obesity." (PMID 36837510, 2023).
HCMV infection (1 paper, 2022). "Cluster 6 includes MYO18A which shows an initial degradation but a rapid increase at later stages of infection, which is in line with MYO18A being repurposed for virus assembly and egress during HCMV infection." (PMID 34982803, 2022).
hearing loss (1 paper, 2024). "These high priority genes, including MPHOSPH8, MYO18A, TRIOBP, OTOGL, TNC, and MYO6, were previously implicated in hearing loss, balance, and cochlear function, and were significantly enriched in common variant studies of hearing loss." (PMID 38943082, 2024).
metastatic prostate carcinoma (1 paper, 2019). A carcinoma that arises from the prostate gland and has spread to other anatomic sites. "MYO18A has been found highly expressed in metastatic prostate cancer and its knockdown affects the cytoskeleton and cell migration." (PMID 31244774, 2019).
Tinnitus (1 paper, 2024). Tinnitus is an auditory perception that can be described as the experience of sound, in the ear or in the head, in the absence of external acoustic stimulation. "Variants in MYO18A have previously been implicated in a study of Swedish MD and tinnitus extreme phenotypes." (PMID 38943082, 2024).
cancer (22 papers, 2010 to 2023). A tumor composed of atypical neoplastic, often pleomorphic cells that invade other tissues. "For the application of the cancer evolutional model, we identify potential evaluation therapeutic targets, such as MYO18A, and FBXW7 genetic mutations in CRCs." (PMID 36009026, 2022). "Unlike the findings in MYO18B, MYO18A was mostly associated with cancers through gene fusion events, with MYO18A frequently found to be fused with other oncogenes such as FGFR1, PDGFRB, and MLL." (PMID 33634131, 2021). "Migration assay of various cancer cell lines also revealed that MYO18A-depleted cells had decreased cell motility." (PMID 33194745, 2020). "The induction of DNA double strand breaks (DSBs) by chemotherapeutic drugs has been shown to activate a cytoplasmic DNA damage response, i.e. the GOLPH3/MYO18A/F-actin pathway, to promote Golgi apparatus dispersal and cancer cells survival." (PMID 32601379, 2020). "MYO18A and FBXW7 intratumor heterogeneity variants are potential targets in the cancer evolution model." (PMID 33194745, 2020). "Nonetheless, exosomal proteins previously reported to be associated with vesicle secretion in cancer cell line supernatants (RAP1A, RAP1B, VAMP1, MYH7, MYO18a, MYOLPF, MYO1E, VPS13B, HSP70) were identified in our samples." (PMID 30764491, 2019). "The phosphorylation of GOLPH3 results in augmented interaction between GOLPH3 and MYO18A, a novel putative cancer driver, well known to be involved in the Golgi pathway." (PMID 31557970, 2019). "Remarkably, the study of Farber-Katz clearly showed that the DNA-PK/GOLPH3/MYO18A pathway is necessary for cell survival of cancer cells after DNA damage, indicating that Golgi fragmentation may contribute to tumor development and maintenance." (PMID 32023813, 2020). "Just like GOLPH3, MYO18A is a driver of human cancers, and several have papers indicated that defective Golgi-to-PM trafficking might contribute to GOLPH3-driven malignant secretory phenotypes." (PMID 32023813, 2020). "Most of the candidate genes of which we confirmed cancer-specific AS in NSCLC are also involved in these processes (ADD3, CLSTN1, FN1, MYO18A, NUMB, SYNE2, and TPM1)." (PMID 21118496, 2010).
tumor (11 papers, 2013 to 2026). "The FISH ALK break-apart positive tumor was found to harbor a novel MYO18A-ALK gene fusion." (PMID 33237469, 2021).
cardiac diseases (1 paper, 2021). "Mutations of either Myo18a or Myo18b cause cardiac developmental defects in mouse, emphasizing their crucial role in muscle development and cardiac diseases." (PMID 33634131, 2021).
hematological malignancies (1 paper, 2018). "In hematological malignancies, MYO18A has been found as fusions with FGFR1, PDGFRB, and MLL in other hematopoietic malignancies." (PMID 30559310, 2018).
MYO18A also shares sentences with these, for which no sentence is quoted: neuroblastoma (5 papers); Alzheimer disease (4); metastatic cancer (2); adenocarcinoma (1); brain cancer (1); brain glioma (1); colorectal cancer (1); deafness (1); glioma (1); hearing (1); histiocytic lymphoma (1); infection (1); melanoma (1); myeloproliferative neoplasm (1); non-small cell lung carcinoma (1); Obesity (1); squamous cell carcinoma (1); Vertigo (1).